HAS3 (hyaluronan synthase 3)
Diseases named in the same sentence as HAS3 in open-access papers (continued):
Sharing a sentence is not in itself a finding about the gene and the disease.
oral cancer (3 papers, 2017 to 2022). "A recent study also showed that HAS3 exerts an oncogenic effect in oral cancer through formation of an inter-regulatory loop with TNF-α33." (PMID 30069008, 2018). "More studies are needed to verify if CD44 is the sole receptor for HA and the involvement of additional SRC-related kinases in HAS3-mediated oncogenic signal axis in oral cancer." (PMID 28107185, 2017). "This study confirmed for the first time that TNF-α with its downstream effector NF-κB activity is a potential inducer for HAS3 overexpression in oral cancer." (PMID 28107185, 2017). "Over-expression and knockdown experiments together with a pharmacological inhibition and anti-HAS3 antibody blockage supported an oncogenic role of HAS3 in oral cancer." (PMID 28107185, 2017). "Endogenous HAS3 silencing also recapitulated the findings of knocking down ectopic HAS3 in oral cancer cells." (PMID 28107185, 2017). "TNF-α, frequently overexpressed in advanced oral cancer tissues, functioned as an upstream inducer for HAS3 transcriptional expression partly through NF-κB activation." (PMID 28107185, 2017). "Hyaluronan synthase 3 (HAS3), involved in pro-inflammatory short chain HA synthesis, was the predominant synthase in oral cancer cells and tissues." (PMID 28107185, 2017). "Since other cytokines also regulate HAS3 expression, their contribution to increasing HAS3 expression in oral cancer remains to be studied." (PMID 28107185, 2017). "TNF-α and HAS3 formed an inter-regulation loop in mediating oral cancer malignancy via NF-κB activation." (PMID 28107185, 2017). "A concordant expression of MCP1 with HAS3 in HAS3-manipulated oral cancer cells further supported a positive role of HAS3 on MCP1 expression." (PMID 28107185, 2017). "Oral cancer cells manifested an increase of HAS3 mRNA and protein expression in most oral cancer lines relative to normal counterparts." (PMID 28107185, 2017). "In this study, HAS3, the most abundant member in oral cancer cells, was increasingly present in oral cancer tissues compared to their normal counterparts." (PMID 28107185, 2017). "HAS3 overexpression significantly increased oral cancer cell migration, invasion and xenograft tumorigenesis accompanied with the increased expression of tumor necrosis factor alpha (TNF-α) and monocyte chemoattractant protein 1 (MCP-1)." (PMID 28107185, 2017). "The expression of HAS3 or TNF-α mRNA was significantly increased in 86 oral cancer relative to adjacent normal tissues." (PMID 28107185, 2017). "To study the role of HAS3 dergulation in oral cancer, we manipulated HAS3 expression in oral cancer lines, OC-2 and OC-3, followed by using various cell-based transformation assays." (PMID 28107185, 2017). "Together, the pharmacological inhibition of HAS enzymatic activity or HAS3 neutralization mimicked HAS3 depletion effects on oral cancer cells, supporting that HA accumulation was accountable for oncogenic actions mediated by HAS3." (PMID 28107185, 2017). "High HAS3 expression further reduced the overall survival for late-stage oral cancer patients (Left, p = 0.073)." (PMID 28107185, 2017). "Together, TNF-α induced the transcriptional regulation of HAS3 expression through a direct binding of activated NF-κB in oral cancer." (PMID 28107185, 2017). "Increased HAS3 mRNA expression was negatively correlated with the overall survival of oral cancer patients." (PMID 28107185, 2017). "Together, enhanced HAS3 expression primarily promoted oral cancer cell migration and invasion while having cell-type specific effect on cell proliferation." (PMID 28107185, 2017). "The increase of HAS3 expression predominantly promoted oral cancer migration and invasion in vitro and xenograft tumorigenesis in vivo." (PMID 28107185, 2017). "Together, a concordant increase of HAS3 with TNF-α expression could potentially serve as a poor prognosis signature for oral cancer." (PMID 28107185, 2017).
oral cancer (continued). "The amount of HA was altered accordingly in the CM derived from HAS3-manipulated oral cancer cells." (PMID 28107185, 2017). "Together, HAS3 was the dominantly expressed HA synthase in most oral cancer cell lines." (PMID 28107185, 2017). "We next examined whether altered HAS3 expression would affect oral cancer cell growth, migration, and invasion." (PMID 28107185, 2017). "We examined by qRT-PCR if TNF-α also stimulated HAS3 mRNA expression in oral cancer cells." (PMID 28107185, 2017). "To examine if TNF-α could increase the in vivo NF-κB binding to the HAS3 promoter in oral cancer cells, we performed ChIP-qPCR analysis of NF-κB sites I and II in P1, III in P2 and IV in P3 promoter regions." (PMID 28107185, 2017). "Understanding the inter-regulation of HA, TNF-α, and HAS3 in oral cancer might facilitate the development of novel therapeutics for treating this disease and many other critical diseases associated with HA deregulation." (PMID 28107185, 2017). "Since TNF-α may function as a upstream mediator for HAS3 expression in oral cancer, we next studied the correlation of TNF-α deregulation with late-stage patients’ clinicopathologic characteristics and clinical outcome." (PMID 28107185, 2017). "Due to the inability of having specific HAS3 protein staining in clinical specimens, we, therefore, investigated the transcript levels of HAS3 and TNF-α in pairwise oral cancer specimens by using qRT-PCR." (PMID 28107185, 2017). "The increase of both HAS3 and TNF-α mRNA expression was correlated with decreased overall survival for oral cancer patients." (PMID 28107185, 2017). "Consistent with a positive role of TNF-α on NF-κB activity and a potential mediation of HAS3 expression by TNF-α, we detected a dose-dependent increase of HAS3 mRNA expression and canonical NF-κB activation in TNF-α-treated oral cancer cells." (PMID 28107185, 2017). "Consistent with TNF-α being an upstream mediator for HAS3 expression, the expression of HAS3 was positively correlated with that of TNF-α in oral cancer specimens." (PMID 28107185, 2017). "Together, HAS3 and TNF-α formed an inter-regulation loop to enhance tumorigenesis in oral cancer." (PMID 28107185, 2017). "The increased TNF-α expression was also observed in HAS3-overexpressing oral cancer cells by qRT-PCR (data not shown)." (PMID 28107185, 2017). "The predominant HAS3 expression was also validated by qRT-PCR analysis in clinical oral cancer specimens regardless of the presence of stromal cells." (PMID 28107185, 2017). "Although HAS3 appears to play a dominant role in oral cancer, we still can not rule out the involvement of HAS1 or HAS2 in HA synthesis nor explain why reduced HA staining was a poor prognositic maker in other oral cancer cohort." (PMID 28107185, 2017). "In addition to TNF-α-mediated HAS3 transcriptional induction, chronic TNF-α exposure induced oral cancer cell stemness." (PMID 28107185, 2017). "In addition to reducing HA accumulation, 4-MU (1 mM) or HAS3 neutralization (10 μg/mL) signficantly attenuated oral cancer cell migration and invasion, and decreased HAS3-mediated increase of relative MCP1 expression in oral cancer cells." (PMID 28107185, 2017). "Despite the detection of both HAS1 and HAS2 in oral cancer cells, their expression levels were lower than that of HAS3 in most oral cancer cell lines not to mention that HAS1 and HAS2 are catalytically less active than HAS3 in HA synthesis." (PMID 28107185, 2017).
prostate carcinoma (3 papers, 2011 to 2023). A carcinoma that arises from epithelial cells of the prostate gland. "While the expression of other prostate cancer EMT markers HAS-3, AHNAK2, TGFBR2, ANXA2, and ANXA3 was higher in DU145 compared with DUTXR (Fig. 1CII–IV)." (PMID 37476073, 2023). "Overexpression of either HAS2 or HAS3 in several tumour types such as prostate cancer, breast cancer, osteosarcoma and colon carcinoma is known to be associated with higher malignancy or metastasis." (PMID 21429221, 2011). "In addition, in prostate carcinoma HAS3 and HAS2 have been shown to produce HA that is broken down by Hyal1 and that subsequently drives tumour progression and even metastasis." (PMID 21429221, 2011). "Importantly, we identified HAS3 as one of the top EMT markers in RNA-seq and scRNA-seq for aggressive prostate cancer that is downregulated by TOPO-METRO treatment." (PMID 37476073, 2023). "scRNA-seq analysis identified higher expression of CSC markers, EMT markers (HAS3 and its receptor CD44), and “stem-like” subclonal cell populations in ARLow/mCRPC/NEPC (PC3, PC3M, and DU145) compared with ARHigh/mCSPC (22RV1, LnCaP) prostate cancer cell lines (Fig. 1BII)." (PMID 37476073, 2023). "Our results are in line with previous studies in prostate cancer, where it was shown that when overexpressing the UGDH enzyme during androgen treatment (similarly eliminated by glucuronidation), the synthesis of HA was not stimulated, although HAS3 expression was increased." (PMID 33572239, 2021).
serous ovarian cancer (3 papers, 2009 to 2019). "We examined expression of HA synthases (HAS1, HAS2, and HAS3) and hyaluronidases (HYAL1, HYAL2) in primary serous ovarian cancer cells isolated from patient ascites and CBP-resistant OV-90 cells." (PMID 31443261, 2019). "Furthermore, we showed that 4-MU inhibited expression of HAS2, HAS3 and CSC markers (ALDHA1 and ABCG2) in a 3D-spheroid culture of chemoresistant primary serous ovarian cancer cells." (PMID 31443261, 2019). "We found that HAS2 and HAS3 but not HAS1 expression is significantly increased in primary serous ovarian cancer cells isolated from the ascites of patients with chemoresistant disease compared to patients with chemosensitive disease." (PMID 31443261, 2019). "Since HAS2 and HAS3 genes showed no consistent increase in their expression in the serous ovarian cancers, and HAS1 mRNA was virtually absent, changes in the transcriptional activity of the HAS genes seem not to be the main factor in the increased hyaluronan content of these tumors." (PMID 19435493, 2009). "We additionally showed that expression of HAS2 and HAS3 but not HAS1 or hyaluronidases HYAL1 and HYAL2 were significantly increased in chemoresistant compared to chemosensitive primary serous ovarian cancer cells." (PMID 31443261, 2019).
bladder cancer (2 papers, 2010 to 2017). "On the other hand, HAS3 mRNA was increased in proliferating post-menopausal endometrium, and has been suggested to promote the growth of bladder carcinoma cells." (PMID 20875124, 2010).
cholangiocarcinoma (2 papers, 2021 to 2023). A carcinoma that arises from the intrahepatic biliary tree (intrahepatic cholangiocarcinoma) or from the junction, or adjacent to the junction, of the right and left hepatic ducts (hilar cholangiocarcinoma). "Conversely, HAS3 exhibited significant upregulation in CESC, cholangiocarcinoma (CHOL), esophageal carcinoma (ESCA), HNSC, KIRC, KIRP, LIHC, LUSC, pheochromocytoma and paraganglioma (PCPG), and UCEC tumors." (PMID 37636435, 2023).
colon adenocarcinoma (2 papers, 2021 to 2023). "In 2 cases of UCEC, 1 case of astrocytoma, 1 case of colon adenocarcinoma (COAD), and 1 case of HNSC, a missense or nonsense mutation was detected in the glycogenin-2-3 domain of HAS3 at amino acid position 330, where arginine (R) was replaced by Q or *." (PMID 37636435, 2023).
endometrial cancer (2 papers, 2010 to 2011). Primary or metastatic malignant neoplasm involving the endometrium (mucous membrane that lines the endometrial cavity). "Of the 50 endometrial cancer cases, the positive immunohistochemical expression was found in 29 cases for HAS1, 33 cases for HAS2, and 29 cases for HAS3." (PMID 21904555, 2011).
glioblastoma (2 papers, 2022). The most malignant astrocytic tumor (WHO grade IV). "In the lung adenocarcinoma cell line A549, HAS2 was expressed at high level, but HAS3 was also expressed to a significant degree, while the glioblastoma cell line U-251MG expressed HAS2, and even higher level of HAS3." (PMID 36497283, 2022). "In previous study, we confirmed that glioblastoma growth could be inhibited by 4MU treatment or HAS3 silencing via inhibiting HA synthesis." (PMID 35410993, 2022). "We found that inhibiting HA synthesis in glioblastoma cells by 4MU treatment or HAS3 silencing regulated macrophages polarization and increased the proportion of M1 macrophages, and that exogenous HA reversed the proportion of M1 macrophages among total macrophages." (PMID 35410993, 2022).
mesothelioma (2 papers, 2019 to 2021). A usually malignant and aggressive neoplasm of the mesothelium which is often associated with exposure to asbestos. "In order to understand whether HAS3 could serve as a potential prognostic target in human MPM, we took advantage of the bioinformatical survival analysis database PROGgeneV2, drawing from The Cancer Genome Atlas Mesothelioma (TCGA-MESO) dataset for the generation of a survival plot." (PMID 33499323, 2021).
metastatic tumors (2 papers, 2022 to 2025). "HAS1 and HAS3 expression is indeed increased in metastatic tumors of HFD-fed mice compared with LFD-fed mice." (PMID 39946200, 2025). "The increase in HAS3 protein levels in metastatic tumors was > 20-fold compared to NK tissues and about fourfold higher than in non-metastatic tumors." (PMID 36581895, 2022).
Obesity (2 papers, 2022). Accumulation of substantial excess body fat. "Regarding HA metabolic turnover, the statistically significant up-regulation of HAS1 in individuals with obesity with no relevant gene expression changes in HAS2 and HAS3 or HA degrading enzymes was confirmed in our previous microarray public data." (PMID 35896710, 2022).
psoriasis (2 papers, 2011 to 2024). An autoimmune condition characterized by red, well-delineated plaques with silvery scales that are usually on the extensor surfaces and scalp. "In all five mouse phenotypes, there was increased expression of S100a9, Lcn2, S100a8, Sprr1b, Mpzl2, Has3, as well as decreased expression of Tppp, Stxbp6, and Cldn23, and each of these effects is consistent with characteristic expression patterns in clinical psoriasis." (PMID 21483750, 2011).
stomach adenocarcinoma (2 papers, 2021 to 2023). "As for HAS3, it showed significant downregulation in BRCA, KICH, LUAD, PRAD, stomach adenocarcinoma (STAD), thyroid carcinoma (THCA), and SKCM tumors." (PMID 37636435, 2023).
aneurysm (1 paper, 2025). Bulging or ballooning in an area of an artery secondary to arterial wall weakening. "Histological analysis of AAA sections using SHG microscopy on day 28 revealed significantly less elastic fiber destruction within the aortic media in Apoe/Has3-DKO compared with Apoe-KO mice, indicating reduced aneurysm pathology." (PMID 41280888, 2025).
Atrophy (1 paper, 2025). Any weakening or degeneration, especially through lack of use. "However, since the Has1−/−; Has3−/− mice do not present MG atrophy or dropout, their MGs are significantly larger at 1 year when compared to 8 weeks." (PMID 40736174, 2025).
Corneal opacity (1 paper, 2025). A reduction of corneal clarity. "In contrast, Has1−/−; Has3−/− mice either did not present any corneal opacity or presented only slight corneal opacity diffused throughout the cornea, with a representative image provided." (PMID 40736174, 2025).
cutaneous melanoma (1 paper, 2018). A primary melanoma arising from atypical melanocytes in the skin. "Consistently, coordinate expression of Id1 or Id3 with HAS2, HAS3 or CD44 significantly correlated with reduced survival of cutaneous melanoma patients." (PMID 30297743, 2018). "Importantly, we found that coordinate expression of Id1 or Id3 with HA synthases HAS2, HAS3, and CD44 is associated with reduced overall survival of cutaneous melanoma patients." (PMID 30297743, 2018).
cystitis (1 paper, 2025). Inflammation of the urinary bladder. "Rapid HAS2 and HAS3 upregulation is in correspondence with other studies looking into ketamine induced cystitis." (PMID 40009603, 2025).
dry eye (1 paper, 2025). "Thus, Has1−/−; Has3−/− mice were protected from ocular surface damage when subjected to the BAC dry eye model when compared to wt mice." (PMID 40736174, 2025). "To further investigate whether the meibum produced by Has1−/−; Has3−/− mice can successfully stabilize the tear film and protect the ocular surface against the deleterious effects of DED, we subjected adult wt and Has1−/−; Has3−/− mice to an experimental model of BAC-induced dry eye." (PMID 40736174, 2025).
dysplastic nevi (1 paper, 2013). "The stromal coverage of HAS3 was significantly reduced in dysplastic nevi and deep melanomas compared to benign nevi (p=0.009 and p=0.030, respectively)." (PMID 23560496, 2013).
endometrial tumors (1 paper, 2010). "The epithelial intensities of HAS1, HAS2 and HAS3 immunostainings were significantly stronger in endometrial tumors compared to normal endometrium (p = 0.001, p = 0.004 and p = 0.003, respectively)." (PMID 20875124, 2010).
endometrioid adenocarcinoma (1 paper, 2011). An adenocarcinoma characterized by the presence of malignant glandular epithelial cells resembling endometrial cells. "In endometrioid adenocarcinoma of uterine corpus, the HAS1, HAS2, and HAS3 were expressed in tumor cells as our previous report." (PMID 21904555, 2011).
endometrioid ovarian cancer (1 paper, 2022). "For HAS3 it concerns OS and PFS of patients with endometrioid ovarian cancer and OS and PFS of patients in grading I. Due to the small number of cases, false tendencies could arise." (PMID 35767191, 2022).
Hypertension (1 paper, 2025). The presence of chronic increased pressure in the systemic arterial system. "However, the phenotype described here, is different: Has3 deficiency did not change AngII-induced hypertension, aortic endothelial function and hypercontractility at the initial phase of AAA/AD development." (PMID 41280888, 2025).
infarction (1 paper, 2025). A localised pathological necrosis of tissue resulting from obstruction of the blood supply usually by a thrombus, an embolus, or vascular torsion. "Interestingly, while Has1 expression was elevated prior to infarction, this increase was no longer present 7 days post‐MI, whereas Has3 expression remained unchanged." (PMID 41250926, 2025).
kidney tumors (1 paper, 2022). "Consistent with the role of HA in promoting tumor growth and metastasis, mice implanted with HAS3-luc transfectant developed visible kidney tumors within three weeks and mRCC in < 5 weeks." (PMID 36581895, 2022).
leukemia (1 paper, 2015). A malignant (clonal) hematologic disorder, involving hematopoietic stem cells and characterized by the presence of primitive or atypical myeloid or lymphoid cells in the bone marrow and the blood. "In fact, HA synthase 3 (HAS3) expression is strongly reduced in CD44v6kd cells, where high HAS3 expression frequently correlates with aggressiveness of carcinoma and leukemia." (PMID 26074915, 2015).
liver fibrosis (1 paper, 2023). "HAS3 knockout mice develop liver fibrosis similar to wild-type mice, suggesting that HAS1 or HAS2 is more likely to regulate liver fibrosis." (PMID 36930869, 2023).
lymph node metastasis (1 paper, 2017). "A concomitant increase of TNF-α, a stimulus for HAS3 expression, with HAS3 expression was not only associated with lymph node metastasis but also negated clinical outcome." (PMID 28107185, 2017).
lymphoma (1 paper, 2013). A malignant (clonal) proliferation of B- lymphocytes or T- lymphocytes which involves the lymph nodes, bone marrow and/or extranodal sites. "Furthermore, chemoresistant lymphoma cell lines were also found to have greater expression of Has1, Has2, and Has3 transcripts, and to secrete higher levels of HA." (PMID 24124770, 2013).
multiple myeloma (1 paper, 2015). "Altered HAS enzymes function has been implicated in multiple myeloma (HAS1), in renal-controlled fluid balance, heart formation, long bone/spine development, wound healing (HAS2), and seizures (HAS3)." (PMID 26448758, 2015).